SDHB (succinate dehydrogenase complex iron sulfur subunit B)
Diseases named in the same sentence as SDHB in open-access papers (continued):
Sharing a sentence is not in itself a finding about the gene and the disease.
renal cell carcinoma (49 papers, 2008 to 2026). "Diagnosis of these variants has profound implications not only for the patient but also their first-degree relatives in terms of risk for PPGLs and other SDHB-associated tumors (renal cell cancer and gastrointestinal stromal tumors)." (PMID 41697738, 2026). "Mutations and deficiencies in SDHB (encoding one of the subunits of SDH in CII) have been linked to early-onset renal cell carcinoma, with abnormal protein disrupting electron flow and increasing ROS production." (PMID 40943457, 2025). "We also evaluated the metabolic effects of alterations to SDH activity in UOK269 cells, a patient derived renal cell carcinoma cell line that arose from a heterozygous point mutation (R46Q) in SDHB and deletion of the other allele." (PMID 36883551, 2023). "We now report a patient with a SDHB mutation, c.166_170del (p.Pro56Tyrfs*5) who developed renal cell carcinomas with characteristic morphological features of SDH-deficient renal cell carcinoma but had positive SDHB immunostaining." (PMID 31092265, 2019). "Regarding other tumors, evaluation for GISTs should be performed in patients with gastrointestinal symptoms, obstruction, or anemia and renal cell carcinoma screening should be performed in patients with SDHB mutations." (PMID 31365623, 2019). "We also confirmed that SDHB knockdown by siRNA enhanced the susceptibility to JQ-1 in a renal cell carcinoma cell line Caki-2." (PMID 28423651, 2017). "In addition, SDHB mutations are related to renal cell carcinoma and T-cell acute leukemia, and SDHB, SDHC, and SDHD mutations result in gastrointestinal stromal tumors." (PMID 34884868, 2021). "In addition, renal cell carcinoma and T-cell acute leukemia are also associated with SDHB mutations." (PMID 31817761, 2019). "SDHB immunostaining may be positive in renal cell carcinoma associated to germline SDHB deficiency which have other typical morphological features." (PMID 31092265, 2019). "In addition, SDHB mutation carriers have been associated with an increased risk of developing other neoplasms, including renal cell carcinoma, gastrointestinal stromal tumors (GISTs) and papillary thyroid cancer." (PMID 27573198, 2017). "SDHB mutation or deficiency has been detected with high frequency in renal cell carcinoma." (PMID 28423651, 2017). "SDHB mutations, known to predispose to PGLs and PCCs, also increase risk of renal cell carcinoma." (PMID 25215250, 2014). "Other tumours associated with mutations in SDHB are renal cell carcinoma (RCC), gastrointestinal stromal tumour (GIST), and pituitary adenoma." (PMID 39000369, 2024). "Many substitutions have been described in the SDHB subunit that are associated with GIST, renal cell carcinoma, multiple hamartomas, acute T-cell leukemia, PHEOs, and PGLs." (PMID 39857410, 2025). "Studies have shown that SDHB and SDHD(Succinate dehydrogenase subunit D) mutations are present in renal cell carcinoma and thyroid tumors." (PMID 37749638, 2023). "Germline mutations within the Krebs cycle enzyme genes fumarate hydratase (FH) or succinate dehydrogenase (SDHB, SDHC, SDHD) are associated with an increased risk of aggressive and early metastasizing variants of renal cell carcinoma (RCC)." (PMID 36455002, 2022). "Mutations in protein subunits of succinate dehydrogenase (SDHA/SDHB/SDHC/SDHD and assembly factor SDHAF2) and fumarate hydratase (encoded by the single gene FH) lead to rare forms of renal cell carcinoma (RCC; denoted by SDHRCC and FHRCC, respectively)." (PMID 35288096, 2022). "SDHB mutations are known to be highly penetrant, with lifetime risk of PGL/PCC as high as 77–100% and lifetime risk of renal cell carcinoma estimated to be 10–20%." (PMID 25215250, 2014). "Research reported that HIF-1α was up-regulated in chronically SDHB-silenced Hep3B cells, HIF-1α was overexpressed in SDH-deficient leiomyomas and renal cell cancer (HLRCC)." (PMID 25491408, 2014). "Complex I activity is deleterious in SDHB-mutant renal cell carcinoma cells." (PMID 36883551, 2023).
renal cell carcinoma (continued). "According to WHO, succinate dehydrogenase (SDH)–deficient renal cell carcinoma is characterized by negative immunostaining for SDHB, which remains positive in non-tumor tissue despite germline mutations in the SDHB gene." (PMID 31092265, 2019). "Of notice, no renal cell carcinomas were detected in our cohort despite a previously reported incidence of 14 % among SDHB mutation carriers." (PMID 27573198, 2017). "SDHB is the most commonly mutated of all the SDH-related genes, with >180 mutations that have been associated with extra adrenal, head or neck paraganglioma, adrenal pheochromocytoma, Carney–Stratakis syndrome, renal cell carcinoma, GIST, and infantile leukodystrophy." (PMID 37508015, 2023). "Heterozygous germline mutations in SDH complex (SDHx) genes (SDHA, SDHB, SDHC, SDHD, and SDHAF2), which act as tumor suppressor genes, predispose to pheochromocytomas and paragangliomas (PPGLs) and rarely to gastrointestinal stromal tumors (GIST), renal cell carcinoma, and pituitary adenomas." (PMID 35892689, 2022). "Although specific mechanisms such as the one elucidated for GISTs are not yet available, research has implicated SDHB and SDHD mutations in renal cell carcinoma and thyroid tumors, SDHB defects in pituitary adenomas, and loss of SDHB in hemangioblastoma." (PMID 33153035, 2020).
gastrointestinal stromal tumor (37 papers, 2012 to 2026). "In this case, immunohistochemical analysis revealed positive SDHB expression, which sharply contrasts with gastrointestinal stromal tumors (GISTs), which typically exhibit SDHB deficiency." (PMID 41333221, 2025). "Patients with SDHB mutation have a relatively high malignancy incidence, ranging from 30% to 41%, with renal cell carcinoma observed in up to 14% and gastrointestinal stromal tumors in 2% of these cases." (PMID 39201746, 2024). "Mutations in SDHA and SDHB have been detected also in gastrointestinal stromal tumors (GISTs)." (PMID 26462158, 2015). "Additionally, mutations in SDHA, SDHB, and SDHC have also been implicated in gastrointestinal stromal tumors." (PMID 28881853, 2017). "SDHB mutations are also associated with the development of RCC (14%), gastrointestinal stromal tumors [GIST; 2%; isolated or associated with PGL (Carney dyad or Carney-Stratakis syndrome) or PGL and chondroma (Carney triad)] and pituitary adenomas (rare)." (PMID 29755524, 2018). "Furthermore, SDHB mutations may result in susceptibility to other malignant tumors, such as renal cell carcinomas, papillary thyroid tumors, neuroblastoma, or gastrointestinal stromal tumor (GIST)." (PMID 26347711, 2015). "Similarly, a significant negative correlation between SDHB and GPT2 mRNA levels were retrieved in human gastrointestinal stromal tumors (GISTs) harboring SDHx mutations." (PMID 37414778, 2023).
head and neck paraganglioma (23 papers, 2004 to 2025). A benign or malignant extra-adrenal paraganglioma arising from paraganglia in the head and neck. "The aim of this study was to evaluate the clinical characteristics and outcome of treatment strategies for patients with head and neck paraganglioma (HNPGL) carrying SDHB germline mutations." (PMID 29951630, 2018). "Of the 37 cases with sporadic head and neck paraganglioma, 2 individuals were identified as carrying heterozygous germline mutations of SDHB (5%)." (PMID 16405730, 2006). "Of the sporadic head and neck paraganglioma cases 8% were found to carry a germline mutation of SDHB or SDHC." (PMID 16405730, 2006). "Notably, hypomorphic pathogenic SDHB variants correlated with increased head and neck paraganglioma occurrence, revealing a genotype-phenotype relationship." (PMID 41252211, 2025). "Germline mutations of SDHB gene are inherited as autosomal dominant with the presence of sympathetic extra-adrenal paragangliomas, followed by adrenal phaeochromocytomas and parasympathetic head and neck paragangliomas." (PMID 29166454, 2017). "In addition, succinate dehydrogenase complex subunit B (SDHB) IHC stain should be routinely performed in all head and neck paragangliomas, and the loss of expression of this marker can help identifying patients with underlying genetic predisposition syndromes to develop these tumours." (PMID 34573868, 2021). "Multiple head and neck paragangliomas are common in patients with SDHD mutations, while malignant head and neck paraganglioma is mostly seen in patients with SDHB mutations." (PMID 26543766, 2015). "In this study we detected germline mutations of SDHB in 5% and of SDHC in 2.5% of sporadic head and neck paraganglioma cases." (PMID 16405730, 2006). "Previously, we showed elevated expression of succinate receptor 1 (SUCNR1) in SDHB PPGLs and SDHD head and neck paragangliomas." (PMID 33776908, 2021). "An even rarer cause for head-and-neck paraganglioma is the SDHAF2 mutation, which should be considered if SDHD, SDHB, and SDHC testing is negative." (PMID 29166454, 2017).
breast carcinoma (18 papers, 2009 to 2024). "In conclusion, loss of SDHA or SDHB expression was detected in approximately 3% of the breast cancers in this study." (PMID 23888270, 2013). "In conclusion, loss of SDHA or SDHB expression was observed in about 3% of breast cancers in this study." (PMID 23888270, 2013). "Interestingly, other types of malignancies (i.e. prostate cancer, lung cancer, breast cancer) are listed as causes of death both in the SDHB- and SDHD-linked cohorts." (PMID 30658386, 2019). "Furthermore, a previous study has reported loss of SDHA or SDHB expression in 3% of breast cancers." (PMID 32156290, 2020). "Indeed, 0.25% and 0.05% of breast cancer exomes carry somatic SDHB and SDHD variants, respectively." (PMID 30658386, 2019). "In comparison, a similar pattern of SDHB mRNA expression was evident in the breast cancer patients with African (n = 179) and European (n = 748) ancestry." (PMID 37810173, 2023). "Further studies will be required to determine the differences in stromal SDHB expression among breast cancer molecular subtypes." (PMID 23888270, 2013). "Immunohistochemical staining for ER, PR, HER-2, Ki-67, HIF-1α, SDHA, and SDHB was performed on tissue microarrays of 721 breast cancers." (PMID 23888270, 2013). "Using similar methods in the present study, we found that 23 of 721 breast cancer patients (3.19%) had SDHA mutation (SDHA–/SDHB– expression) and one patient (0.1%) had an SDHB mutation (SHDA+/SDHB– expression)." (PMID 23888270, 2013). "SDHB and SDHD variants are highly related to the increased prevalence of breast cancers." (PMID 32156290, 2020). "SDHA-negative breast cancers were associated with younger age at diagnosis (P = 0.012), and SDHB-negative breast cancers with lower histologic grade (P = 0.044) and lower Ki-67 labeling index (LI) (P = 0.046)." (PMID 23888270, 2013). "Compared with the control group, OXPHOS-associated factors (NDUFA9 and SDHB) showed an obvious expression increase in YB1-silenced tumors, but the expression of HMGA1 was decreased significantly, suggesting the existence of an RNA displacement model in YB1-mediated breast cancer progression." (PMID 37035211, 2023). "One female breast cancer patient tested positive for PGVs in both BRIP1 and NF1, while one patient with splenic cancer harbored PGVs in both SDHB and BUB1B." (PMID 34830767, 2021). "In this study, more than 50% of breast cancers expressed SDHA and SDHB, which are key components of aerobic glucose metabolism through the TCA cycle and mitochondrial electron transport." (PMID 23888270, 2013). "Clinicopathologic characteristics of breast cancers were compared between the SDHA/SDHB positive and negative breast cancers." (PMID 23888270, 2013). "Similarly, the SDHA+/SDHB- and SDHA-/SDHB- breast cancers in this study were distinguished by lower histologic grade, and in the SDHB-negative tumors, by lower Ki-67 LI." (PMID 23888270, 2013). "Patients with SDHA- and SDHB-negative breast cancers were also younger than patients with intact SDH expression, although in the case of SDHB, this difference was not statistically significant." (PMID 23888270, 2013). "No DNA methylation was identified in the promoter regions of the SDHA, SDHB, SDHC, SDHD and FH genes in 72 breast carcinomas and 10 breast cancer cell lines using methylation-sensitive high resolution melting which detects both homogeneous and heterogeneous methylation." (PMID 19778456, 2009). "However, stromal cells did not express SDHA and SDHB in most breast cancers in this study, which made it impossible to compare the staining intensity between tumor cells and internal normal controls (stromal cells)." (PMID 23888270, 2013). "Although most breast cancers in this study were negative for SDH in stromal elements, stromal SDHB expression differed significantly among the molecular subtypes." (PMID 23888270, 2013).
breast carcinoma (continued). "In conclusion, promoter methylation of the SDHA, SDHB, SDHC, SDHD and FH genes is unlikely to be an important mechanism in stabilising HIF-1 in breast carcinomas through the downregulation of the expression of SDH and FH genes." (PMID 19778456, 2009). "However, in a previous study, stromal cells in breast cancer did not express mitochondrial metabolic enzymes (cytochrome c oxidase, NADH, or SDHB)." (PMID 23888270, 2013).
colorectal cancer (17 papers, 2014 to 2025). A primary or metastatic malignant neoplasm that affects the colon or rectum. "Reduced SDHB protein expression was also associated with growth and de-differentiation of colorectal cancer cells." (PMID 25694510, 2015). "Reduced SDHB expression is associated with growth and de-differentiation of colorectal cancer cells." (PMID 25491408, 2014). "Research has demonstrated that changes in SDHB expression can serve as a prognostic indicator in cancers such as colorectal cancer and clear cell renal cell carcinoma." (PMID 40724918, 2025). "Next, we examined the expressions of genes encoding mitochondrial components (SDHB, UQCRC2) and LDs in tumor tissues of colorectal cancer patients or in tumor grafts." (PMID 39856069, 2025). "It has been reported that succinate dehydrogenase B subunit (SDHB) knockdown contributes to colorectal cancer cell invasion and migration via EMT by activating the TGF-β signaling pathway through SNAIL1-SMAD3/SMAD4." (PMID 36115986, 2022). "It was reported that SDHB was downregulated in colorectal cancer due to the upregulation of miR-142-5p." (PMID 34094922, 2021). "The low expression of SDHB promotes aerobic glycolysis, and the lack of SDHB function leads to the occurrence and development of multiple kinds of tumors, including liver cancer and colorectal cancer etc.." (PMID 34094922, 2021). "SDHB acts as suppressor tumor gene in colorectal cancer, and SDHB knockdown could promote tumor growth factor beta (TGFβ) signal pathway in CRC cells, which activates epithelial–mesenchymal transition (EMT)." (PMID 36505872, 2022). "The low expression of SDHB has been shown to promote aerobic glycolysis, and the lack of SDHB function has been implicated in the occurrence and development of multiple kinds of tumors, including liver cancer, renal cancer and colorectal cancer." (PMID 35004842, 2021). "Kitazawa and others deleted SDHB in HCT116 cells (of colorectal cancer origin) by CRISPR to make an effective drug-screening survey.2.1.2Saccharomyces cerevisiae, or yeast, has contributed significantly to understanding the molecular pathogenesis of tumorigenesis resulting from defective SDH." (PMID 34957538, 2021). "We therefore propose that the inferred regulators of SDHB could be valid potential regulatory targets for colorectal cancer treatment." (PMID 33168813, 2020). "Additionally, miR-142-5p can promote the development of colorectal cancer by targeting SDHB." (PMID 38844980, 2024). "Decreased SDHB expression has been reported in both human colorectal cancer (CRC) samples and CRC cell lines, and reduced SDHB activity has been correlated with a more advanced clinical lymphatic and distant metastatic phenotype." (PMID 31822964, 2020). "Therefore, the specific effect of JQ-1 on SDHB-deficient cells may not be limited to colorectal cancer." (PMID 28423651, 2017). "In colorectal cancer, the lack of SDHB promotes TGFβ-mediated colorectal cancer invasion and metastasis through the transcriptional inhibitory complex SNAIL1-SMAD3/4." (PMID 38844980, 2024).
von Hippel-Lindau syndrome (13 papers, 2005 to 2025). "Extra-adrenal pheochromocytomas can be associated with hereditary conditions such as multiple endocrine neoplasia (MEN) type 2, von Hippel-Lindau syndrome, or mutations in the SDHB, SDHD, or RET gene." (PMID 39867070, 2024). "Genetic information was available in 136 patients of the PHEO group, of whom 31.6% had a predisposing hereditary syndrome (27 MEN2A, 6 neurofibromatosis type 1, 4 SDHB mutations, 3 Von Hippel Lindau syndrome, 2 SDHD mutations and 1 patients MAX mutation)." (PMID 35177692, 2022). "PCC occurs sporadically or within hereditary syndromes like von Hippel-Lindau disease (VHL), multiple endocrine neoplasia type 2 (MEN2), or neurofibromatosis type 1 (NF1), with mutations, particularly SDHB, increasing malignancy risk." (PMID 40927285, 2025). "The hereditary PHEO appears as a component of multiple endocrine neoplasia type 2 (MEN 2), von Hippel–Lindau disease (VHL), neurofibromatosis type 1 (NF1) or familial paraganglioma syndromes (caused by mutations of SDHD and SDHB genes)." (PMID 24675699, 2014). "Due to histopathologic diagnosis, genetic testing for familial paraganglioma, neurofibromatosis type 1, von Hippel-Lindau disease, the Carney triad, multiple endocrine neoplasia type 2, and mutations of the succinate dehydrogenase genes (SDHB, SDHC, and SDHD) was performed that was negative." (PMID 17683569, 2007).
neurofibromatosis type 1 (12 papers, 2007 to 2025). A clinically heterogeneous, neurocutaneous genetic disorder characterized by cafe-au-lait spots, iris Lisch nodules, axillary and inguinal freckling, and multiple neurofibromas. "Nine patients had a genetic syndrome, SDHB or SDHD-related PGL in seven, neurofibromatosis type 1 in two, four patients were classified as sporadic cases, and genetic testing had not been performed in nine patients." (PMID 31261748, 2019).
Carney-Stratakis syndrome (11 papers, 2013 to 2025). Carney-Stratakis syndrome is a recently described familial syndrome characterized by gastrointestinal stromal tumors (GIST) and paragangliomas, often at multiple sites. "Based on a summary of reported Carney-Stratakis syndrome cases, we found that germline mutations in the SDHB and SDHD genes were the most common." (PMID 36387130, 2022). "Most pediatric GISTs and GISTs in patients with Carney triad or Carney-Stratakis syndrome are SDHB-deficient." (PMID 31100836, 2019). "Recently those GISTs associated with Carney Triad, Carney-Stratakis syndrome, along with young and pediatric GISTs have been documented to have a loss of succinate dehydrogenase subunit B (SDHB) expression, a mitochondrial protein." (PMID 24386562, 2013).